CALR (calreticulin)
Diseases named in the same sentence as CALR in open-access papers (continued):
Sharing a sentence is not in itself a finding about the gene and the disease.
cancer (continued). "Extracellular calreticulin, also called ecto-calreticulin, regulates diverse cellular activities, such as antigen processing and presentation, phagocytosis of apoptotic and cancer cells as well as cell adhesion, migration and proliferation." (PMID 23585889, 2013). "Studies have shown that CALR plays an important role in the biological processes of many cancers, and these mechanisms are mediated via antiangiogenic factors and the immune response." (PMID 22293781, 2012). "On the other hand, it has been shown that doxorubicin induces immunogenic cell death in cancer cells through the calreticulin exposure pathway as well as inflammasome activation in the phagocytic cells." (PMID 22768222, 2012). "Examples provide dual-polarization quantification of biotin binding to a silane-coated sensor as well as binding of the cancer biomarker protein calreticulin to its monoclonal IgG capture antibody." (PMID 22319364, 2011). "Further, purified preparations of HSC70, gp96, HSP70, and calreticulin isolated from cancer cells have been shown to elicit cancer-specific immunity against a wide range of cancers in animal models." (PMID 12966429, 2003). "In contrast, the levels of some members of the stress protein family (pHSP60, HSP90 and calreticulin) were higher in carcinomas." (PMID 8932346, 1996). "Therapeutically, combining agents that enhance CALR surface exposure with CD47 blockade on cancer cells may synergistically promote their selective clearance while minimizing off-target immune activation." (PMID 40650935, 2025). "Neoadjuvant chemotherapy promotes TLS formation, adaptive immunity, and maturation in metastatic HCSOC lesions.Intracellular calreticulin (CALR) expression within cancer cells, a marker of endoplasmic reticulum stress and potential cell death, was increased.Suggests clinical trial with chemo + ICI." (PMID 40475770, 2025). "Immune‐related proteins–osteopontin (Spp1), lactotransferrin (Ltf), calreticulin (Calr) and peroxiredoxin 2 (Prdx2)–were associated with systemic myeloid‐derived suppressor cell (MDSC) burden, highlighting their potential roles in malignant tumors." (PMID 39939411, 2025). "Notably, elevated FGD3 increased release of DAMPs, strongly enhanced exposure of immunogenic cell surface calreticulin and increased sensitivity of cancer cells to NK cell-mediated lysis." (PMID 41225536, 2025). "Moreover, CALR’s role in modulating immune responses, such as macrophage recruitment and polarization, further emphasizes its involvement in immune-related cancer processes." (PMID 39469643, 2024). "It is known that some chemotherapy drugs may induce ICD characterized by high expression of calreticulin (CRT) on the surface of dying cancer cells, thereby inducing effective immune responses." (PMID 38594751, 2024). "The mutated CALR neoantigen is an ideal target for therapy because it is expressed specifically by the cancer cells and not normal cells." (PMID 39682299, 2024). "Such a translocation of CALR and its dissociation from POLB exhibit some degree of heterogeneity that is linked to cell type and initiating trigger, resulting in varying expression and functions of Calr in different types of normal and cancer settings." (PMID 38245510, 2024). "As phagocytosis induction depends on the balance between many eat-me and don't-eat me signals on the cancer cell surface, the increase of only one of them (for example, calreticulin) may be insufficient to have an impact." (PMID 39196415, 2024). "Therefore, we extensively validated the upregulation of CALR in a panel of ALK-positive cancer cell lines after the administration of fixed doses of TKIs, showing the overexpression of this “pro-eat me” signal at the concentrations used." (PMID 39767726, 2024). "Some studies have found that the ER stress involved in ICD is PERK-dependent eIF2α phosphorylation related to CALR exposure, and ER stress response-elicited CALR exposure may contribute to cancer immunosurveillance." (PMID 39090653, 2024).
cancer (continued). "We investigated whether CALR surface expression was upregulated after exposure to fixed concentrations of TKIs in a panel of ALK-positive cancer cell lines available in our institution." (PMID 39767726, 2024). "In conclusion we have shown that therapeutic cancer vaccination against mutant CALR does not result in enrichment of mutation specific T cells in the bone marrow." (PMID 37662956, 2023). "CALR was long thought to be a pro‐phagocytic signal expressed on the surface of cancer cells." (PMID 37409695, 2023). "Thus overall, we have found that CALRmut specific T cells do not enrich in the bone marrow in patients that have received therapeutic cancer vaccines against mutant CALR." (PMID 37662956, 2023). "The 4T1 cancer cell line exposed the largest quantity of calreticulin." (PMID 37239831, 2023). "Moreover, cancer-homing properties are associated with cancer cell membrane surface adhesion molecules (CCAM), such as selectins, calreticulin, integrins, immunoglobulin superfamily (Ig-SF), and lymphocyte homing receptors." (PMID 38140108, 2023). "Challenge also apply on specifying the concentration at which CALR deficiency can inhibit this pathway taking into account the potential of cancer cells to escape immune-surveillance by suppressing the CALR exposure pathway at multiple levels (Tallarida, 2011)." (PMID 36998701, 2023). "One possible explanation for the differing results may be that CALR has been reported to be overexpressed at the membrane level of cancer cells." (PMID 36907982, 2023). "Cancer cells undergoing ICD contribute to the emission of immuno-stimulatory molecules, such as damage-associated molecular patterns (DAMPs), the most common of which are ATP, high-mobility group box 1 (HMGB1), and calreticulin (CRT)." (PMID 37896190, 2023). "Calreticulin (CALR) has served distinct physiological roles in cancer malignancies; nonetheless, impact of radiation on chaperones and molecular roles they play remains largely unknown." (PMID 36644580, 2023). "Furthermore, calreticulin mutants secreted from malignant cells inhibit phagocytosis of dying cancer cells by dendritic cells resulting in immunosuppressive effects." (PMID 37424156, 2023). "Upon the discovery of the CALR exon 9 mutations in MPN it was speculated that the mutations could be targeted by the immune system and thus used for cancer immune therapy." (PMID 37662956, 2023). "Therefore, the multifunctionality of CALR renders it a significant factor in the pathogenesis of diverse diseases, encompassing cancer and autoimmune disorders." (PMID 38023241, 2023). "Thus, autophagy induces the ICD of cancer cells through the release of ATP and the exposure of calreticulin." (PMID 36814780, 2023). "Hence, the downregulation of CALR can have oncogenic effects because of the impairment of physiological homeostasis and the reduced stimulation of immune surveillance against cancer cells." (PMID 37947594, 2023). "Besides, in the GBM single cell sequencing dataset GSE138794, CALR was abundantly expressed in cancer cells and macrophages based on Dimplot and Vlnplot." (PMID 35418980, 2022). "To confirm this hypothesis, we first investigated the ability of NBTXR3 + RT to modulate calreticulin exposure on cancer cell surface membrane (also called ecto-calreticulin or Ecto-CALR), a biomarker of ICD." (PMID 35659676, 2022). "This indicated that tissue type might not be an essential determinant contributing to ICD state of cancer patients; instead, a few high-expressed genes including CALR, HSP90AA1 and PDIA3 could regulate the process of ICD at a pan-cancer level." (PMID 36497433, 2022). "Cancer cells undergoing ICD require cell surface calreticulin (CRT) exposure, induction of EIF2α-dependent reticulum stress, high mobility group box 1 (HMGB1) and ATP release, and the expression of type 1 IFNs (Ifnα1 and Ifnβ1) and chemokines (Cxcl 9 and Cxcl 10)." (PMID 36090972, 2022).
cancer (continued). "Our research group has designed several DNA vaccines with enhanced antitumor effects by using E6 and/or E7 antigens from HPV-16 fused to a signal peptide from calreticulin to direct the antigen expression to the ER using the biolistic delivery method in a murine cancer model." (PMID 36145609, 2022). "The lectin chaperones calreticulin (CALR) and calnexin (CANX), together with their co-chaperone PDIA3, are increasingly implicated in studies of human cancers in roles that extend beyond their primary function as quality control facilitators of protein folding within the endoplasmic reticulum (ER)." (PMID 35860021, 2022). "Calreticulin will expose on the cell surface when cancer happens to ICD." (PMID 39188744, 2022). "We first analyzed the CALR expression in pan-cancer based on the TCGA database." (PMID 35264066, 2022). "Interestingly, chemotherapy drugs can induce calreticulin exposure onto the cancer cell surface, leading to maturation of DC and activation of tumor-specific effector T cells." (PMID 35432318, 2022). "In addition to this, docetaxel also induces calreticulin translocation to the plasma membrane of the dying cells and triggers phagocytosis of the cancer cells by TAMs." (PMID 36679900, 2022). "The effect of CALR on the prognosis of malignant tumors was controversial." (PMID 36579538, 2022). "Of these DAMPs, calreticulin (CRT) is key for promoting phagocytic uptake of cancer cells by APCs." (PMID 34069922, 2021). "After migration to the site of inflammation, exposure of neutrophils to ‘eat me’ signals, such as PS and calreticulin, results in the polarization to pro-inflammatory phenotype and, consequently, to cytotoxicity towards remaining cancer cells that survived the therapy." (PMID 34485114, 2021). "Expression of calreticulin makes cancer cells visible to the immune system." (PMID 33799560, 2021). "Increasing evidence suggests that CALR can be released by cancer cells and may serve as a predictive biomarker." (PMID 34944879, 2021). "Thus, future trials employing therapeutic cancer vaccinations against mutant CALR should aim to combine the vaccines with other treatments." (PMID 33718228, 2021). "CALR was up-regulated in 16 types of tumors compared with the corresponding normal tissues, which indicated that CALR may play an oncogenic role in most cancer types." (PMID 34910788, 2021). "The extracellular release of high mobility group box 1 (HMGB1) and adenosine triphosphate (ATP) attracts and activates antigen-presenting cells (APCs), and the translocation of calreticulin (CRT) on the surface of dying cancer cells serves as an “eat-me” signal to phagocytes." (PMID 33478072, 2021). "Studies carried out with cancer cells showed that their phagocytosis might depend on the levels of calreticulin expressed in their cell membrane as well as its secretion." (PMID 34638556, 2021). "However, consistent with the calreticulin data, the co-culture of cancer cells treated with Dox and siCD47 showed a pronounced increase in uptake compared to either siCD47 or Dox." (PMID 34522209, 2021). "Moreover, it was demonstrated that anthracyclines, in particular doxorubicin, enhance an anticancer-immune activity by inducing calreticulin (CRT) exposure on dying cancer cell, which is a fundamental step for ICD mediated by DCs." (PMID 36046087, 2021). "High levels of CALR have been shown to adversely affect patient survival in a variety of cancers." (PMID 34162346, 2021). "Furthermore, a multi-functional protein calreticulin has been demonstrated as an important pro-phagocytic “eat me” signals for apoptotic cells and many types of cancer cells." (PMID 33790906, 2021). "However, calreticulin normally resides inside of the cells, and needs to be translocated to the surface of the cancer cells to be detected by DCs." (PMID 33918635, 2021). "Calreticulin, antigen expressed on the surface of cancer cells, can also activate DC phagocytosis." (PMID 33918635, 2021).
cancer (continued). "Whether induction of calreticulin translocation in cancer stem cells is a unique effect observed after PrRT remains to be elucidated." (PMID 33806808, 2021). "Cancer cells gain many advantages over normal tissue by dysregulating calreticulin since it is a critical modulator of Ca2+ ion-dependent processes including proliferation, differentiation, cell adhesion, migration, intercellular interactions, immune response, and apoptosis." (PMID 34572262, 2021). "Therefore, serum CALR is considered as a useful biomarker in cancer diagnosis and prognosis evaluation." (PMID 32082309, 2020). "The expression/behavior of calreticulin in CSCs and cancer cells undergoing EMT (i.e., CSC precursors) may be modulated by means of small molecule compounds." (PMID 32268506, 2020). "Previous studies have shown that CALR is a prognostic factor for several human cancers." (PMID 33221760, 2020). "In the case of CALR, there was only a single position under selection within the cancer risk region, but it was not directly targeted by cancer mutations." (PMID 32731489, 2020). "As the CALR mutations are cancer-specific mutations, healthy donor T cells are not expected to display any reactivity against mutant CALR epitopes." (PMID 32630667, 2020). "RT induces immunogenic cancer cell death, which results in calreticulin (CRT) exposure on the cells surface and the release of tumor neoantigens as well as death-associated molecular patterns (DAMPs; among others, adenosine triphosphate (ATP) and high mobility group box 1 (HMGB1) protein)." (PMID 32605154, 2020). "Last but not the least, to better understand the potential roles and clinical relevance of CALR in multiple human cancers, the expression profiles of CALR were further investigated across 33 major types of human cancer in The Cancer Genome Atlas (TCGA) database." (PMID 32508042, 2020). "Cancer cells dying by immunogenic cell death release damage associated signals including adenosine triphosphate (ATP), calreticulin and high mobility group box 1 (HMGB1) that promote maturation of immature dendritic cells (DCs) adjacent to the dying cancer cells." (PMID 32937841, 2020). "Retrospectively monitoring CALR/HSP expression in formalin-fixed paraffin-embedded bioptic samples from cancer patients by immunohistochemistry coupled to the evaluation of clinicopathological variables, offers a tool to estimate the impact of CALR/HSP exposure on disease progression." (PMID 33243969, 2020). "First, the translocation of calreticulin (CRT) from the perinuclear ER to the cancer cell membrane concomitantly with the re-localization of ERp57 will work as an “eat me” signal to induce phagocytosis by DCs, along with the induction of antigen presentation to activate antigen-specific T cells." (PMID 32656498, 2020). "One of such signals, i.e., the exposure of calreticulin (CALR) on the membrane of malignant cells experiencing endoplasmic reticulum (ER) stress, is well known for its role in the activation of immune responses to dying cancer cells." (PMID 31747968, 2019). "Calreticulin has been also utilized as therapeutic adjuvant in cancer." (PMID 31814876, 2019). "It is conceivable that the immune surveillance program may help to remove cells with aneuploidy, perhaps by recognizing specific cell surface antigens such as calreticulin, to suppress the growth of cancer cells." (PMID 31729408, 2019). "Second, CD47 and calreticulin cell surface protein levels on cancer cells were highly correlated." (PMID 32038992, 2019). "A thorough analysis of the immune constitution of such individuals might add important new information on the development and evolution of CALR-mutant MPN, which could potentially be prevented by therapeutic cancer vaccination with CALR-mutant epitopes." (PMID 30655510, 2019). "A correlation between CALR expression and tumorigenesis has been studied in a variety of cancers." (PMID 29443896, 2018).
cancer (continued). "We used qRT-PCR to investigate the expression of HSPs, calreticulin (CALR) (an “eat me signal” molecule expressed in the surface of cancer cells that promotes their removal by cells of the immune system), B2M and SAHAI-01, a classical MHC-I molecule of the Tasmanian devil." (PMID 29702669, 2018). "Following exposure to photosensitizers, multiple human cancer cell lines showed the surface expression of CALR and released ATP before the signatures of apoptosis could be detected." (PMID 29666625, 2018). "Calreticulin is located at the cell membrane and functions as an “eat me” signal and brings the cancer cells to their microenvironment, such as by the extracellular matrix (ECM) in an inside-out or outside-in signaling manner through integrins or the cytoskeletal protein network." (PMID 30598998, 2018). "Interestingly, CALR is thought to function as a pro-phagocytic signal highly expressed on the surface of several human cancers, but minimally expressed on normal cell counterparts line." (PMID 27566066, 2016). "Accumulating clinical evidence indicates that various parameters linked to ICD-associated CALR and HSP signaling may have prognostic or predictive value for cancer patients." (PMID 26300886, 2015). "In addition, certain anti-cancer therapies induce the translocation of calreticulin from the ER to the cell surface of dying cancer cells, where calreticulin dictates the immunogenicity of these cells." (PMID 25750898, 2015). "Interestingly, also treatment of cancer cells with a recombinant form of the tumor necrosis factor (TNF)-related apoptosis inducing ligand (TRAIL) was reported to induce calreticulin exposure and ICD." (PMID 25750898, 2015). "Thus, ways of reliably and uniformly inducing calreticulin exposure in cancer patients will have to be identified." (PMID 25688334, 2015). "Recently, ERp57 was reported to contribute to calreticulin translocation on the cell surface in the process of immunogenic cell death, which is an important factor for a favorable outcome in response to chemotherapy treatment of cancer cells." (PMID 25605256, 2015). "Interestingly, treatment with tumor necrosis factor (TNF)-related apoptosis inducing ligand (TRAIL) also induces membrane calreticulin exposure on cancer cells." (PMID 25750898, 2015). "Calreticulin(CRT) is aberrantly overexpressed in many human cancer cells." (PMID 26307067, 2015). "In addition to immunogenicity and tumorigenesis, interactions between calreticulin and integrins have been described during cell adhesion, which is an essential process for cancer metastasis." (PMID 25918716, 2015). "Moreover, several reports reveal that manipulation of calreticulin levels profoundly affects cancer cell proliferation and angiogenesis as well as differentiation." (PMID 25918716, 2015). "The molecular mechanisms of immunogenic modulation include a) changes in the surface phenotype of cancer cells, including exposure of calreticulin on the outer leaflet of the plasma membrane, b) down-regulation of antiapoptotic and/or prosurvival genes, and c) modulation of components of the APM." (PMID 25344864, 2014). "However, this increased killing was abrogated in carcinoma cells with reduced expression of calreticulin or PERK (P < 0.0001)." (PMID 24480782, 2014). "Recently, the unique ability of doxorubicin, daunorubicin and mitoxantrone to make cancer cells immunogenic was shown to be through calreticulin re-localization to the cell surface and the selective induction and release of High-mobility group box 1 (HMGB1) protein from dying cancer cells." (PMID 20626886, 2010). "Indeed, the combination use of PTT and chemotherapy led to synergistically induced pyroptosis in cancer cells, exposing calreticulin on the surface of cancer cells and induced maturation of dendritic cells and production of different immunocytokines which led to the activation of immune responses." (PMID 39373299, 2024).